TNF (tumor necrosis factor)
Diseases named in the same sentence as TNF in open-access papers (continued):
Sharing a sentence is not in itself a finding about the gene and the disease.
breast carcinoma (continued). "The results described here indicate that the direct target of TNF-α in the Hs578T breast cancer cell line increases the level of certain pro-apoptotic factors that modulate different cellular networks that direct the cells towards death." (PMID 23263670, 2012). "Based on observations with SK-BR-3 cells, we analyzed interactions between anti-HER2 antibodies and TNF-α, using five different breast cancer cell lines." (PMID 23033967, 2012). "It was reported that over-expression of PrP in MCF7 breast cancer cells inhibit tumor necrosis factor alpha (TNF)- or Bax-induced cell death." (PMID 23133614, 2012). "It has been previously reported that amplified expression of HER2 in breast cancer cells induces resistance to TNF-α cytotoxicity that can be sensitized by Trastuzumab." (PMID 23033967, 2012). "Our aim was to generate novel anti-HER2 monoclonal antibodies inhibiting the growth of breast cancer cells, either alone or in combination with tumor necrosis factor-α (TNF-α)." (PMID 23033967, 2012). "For example, tumour-associated macrophages were shown to induce sublethal oxidative stress in murine mammary tumour cells, possibly through the secretion of the inflammatory cytokine tumour necrosis factor-α (TNF-α)." (PMID 23119185, 2012). "Nishimoto observed rapid increases of interleukin 12, interferon γ, and TNF-α values in the blood of a breast cancer patient (45-years-old female) after oral administration of 200 mL fucoidan extract solution (40 mg/kg/day) for 1.5 and 4 months." (PMID 22096572, 2011). "Inhibition of ERK was associated with a decrease in autophagy and increased cellular sensitivity to tumor necrosis factor-α (TNF) in breast cancer MCF-7 cells." (PMID 24212825, 2011). "TNF-α also imparts breast cancer cells with a stem cell-like phenotype by inducing Slug expression via NFκB, a major transcription factor that functions downstream of TNF-α." (PMID 22187661, 2011). "This study investigated the effects of Ulinastatin (UTI) and docataxel (Taxotere, TAX) on tumor growth and expression of interleukin-6 (IL-6), interleukin-8 (IL-8), and tumor necrosis factor-α (TNF-α) in breast cancer." (PMID 21345194, 2011). "To determine if this indeed the case, we have initiated this study by determining the expression patterns of CCL2, CCL5, TNFα and IL-1β in biopsy sections of healthy individuals and in breast cancer patients at different progression stages of disease." (PMID 21486440, 2011). "Intracellular signalling pathways triggered by TNF-α leading to numerous tumors have been partially delineated, with NF-κB playing an important role especially in breast cancer cells." (PMID 21754991, 2011). "Altogether, these data suggest that dysregulated/TNF-α stimulated endothelial cells through NF-κB are likely to play an important role in breast cancer." (PMID 21754991, 2011). "In this study, we asked if associations exist between the inflammatory chemokines CCL2 & CCL5 and the inflammatory cytokines TNFα & IL-1β in breast cancer." (PMID 21486440, 2011). "In our study, the analysis of serum cytokines revealed higher expression of IL-17, IFN-γ, and TNF-α in ST2−/− mice challenged with 4T1 breast cancer cells." (PMID 21484786, 2011). "Mainly, the findings on TNFα contribute to the overall view of the roles played by this cytokine in breast cancer." (PMID 21486440, 2011). "In this study, we have identified the relationships between inflammatory chemokines and cytokines in breast cancer along different stages of disease, and have analyzed the potential roles of TNFα and IL-1β in promoting breast cancer progression." (PMID 21486440, 2011). "As TNFα has been shown to be present in the tumor microenvironment of a significant proportion of human infiltrating breast cancers, it would have clinical implication in HER2-positive breast cancer treatment." (PMID 22295219, 2011).
breast carcinoma (continued). "The inflammatory chemokines CCL2 (MCP-1) & CCL5 (RANTES) and the inflammatory cytokines TNFα & IL-1β were shown to contribute to breast cancer development and metastasis." (PMID 21486440, 2011). "In vivo, AMT showed some antitumor activity in tumor xenograft models of colon and mammary cancer, and in immune stimulation via induction of IL-6 and tumor necrosis factor (TNF)-alpha in human peripheral blood mononuclear cell (PBMCs)." (PMID 21943068, 2011). "One out of the eight patients under treatment with anti-TNFα died (breast cancer), and the one patient under treatment with anakinra (lung cancer) died." (PMID 20064207, 2010). "One study showed that breast cancer cells, which are typically resistant to TNFα-induced apoptosis, demonstrated enhanced apoptosis and prolonged activation of JNK when expressing mIκBα." (PMID 20492683, 2010). "A correlation between IL-1 and TNF-α levels and the response of the tumor to treatment was found in patients with breast cancer, with a better clinical response following low levels of IL-1 and TNF-α." (PMID 20184737, 2010). "TNF-α is a known pro-inflammatory cytokine and generates an autocrine tumor promoting network in ovarian and breast cancer." (PMID 19643025, 2009). "In our study, serum analysis of cytokine proteins revealed higher expression of M-CSF, IL-17, IL-6, TNF-α, and VegF in the arthritic mice only when challenged with 4T1 metastatic breast cancer cells." (PMID 19643025, 2009). "The cells were stimulated for 3 h with either TNF (10 ng/ml) or TSF's derived from breast cancer cells lines: MCF-7 and ZR75.30 (1 μg/ml), (labeled TSFMCF-7 and TSFZR75.30, respectively), diluted in M-199 medium." (PMID 19930605, 2009). "In advanced breast cancer, TNF-α and polyI:C have also been used before as maturation stimuli and to induce secretion of IL-12." (PMID 18588665, 2008). "Over-expression of PrPC has also been reported to render MCF-7 breast carcinoma cells resistant to apoptosis induced by TNF-α, TRAIL, and Bax." (PMID 18718018, 2008). "In the first set of experiments, we found that PrP over-expression had a minimal effect on the death of MCF-7 breast carcinoma cells treated with TNF-α and Prn-p0/0 immortalized hippocampal neurons (HpL3-4 cells) subjected to serum deprivation." (PMID 18718018, 2008). "The expression level and localization pattern of CD44v4 in breast cancer cells is closely correlated with tumor cell migratory capability across TNF-α pre-activated HUVEC monolayers." (PMID 18350162, 2008). "Most importantly, in companion experiments IL-17 directly induced breast cancer cell invasion independently of TNFα." (PMID 19014637, 2008). "Stable overexpression of BP1 led to inhibition of apoptosis in MCF7 breast cancer cells challenged with TNFα." (PMID 17854498, 2007). "In this report, we show that the ERα protein level in breast cancer cells is regulated by TNFα and PI3-kinase, which has important implications on the transrepression function of ERα." (PMID 14970864, 2004). "By reducing basal and/or TNFα-induced IL-6 expression, ERα can reduce multidrug-resistant growth of breast cancer cells." (PMID 14970864, 2004). "In mammary carcinoma and sarcoma models, TNFα was shown to significantly increase tumour radiocurability even when TNFα was injected 3 h after RT." (PMID 14612914, 2003). "We have investigated SNPs in genes including TNF-α, VEGF and Endostatin for associations with breast cancer severity and susceptibility." (PMID 12402142, 2002). "We have used the nitrosomethylurea-induced rat mammary tumour model to study the effects of parenteral administration of human recombinant tumour necrosis factor (rHu-TNF) and rat gamma interferon (IFN-gamma)." (PMID 2495016, 1989).
breast carcinoma (continued). "IL-1, generated by immune cells such as macrophages and lymphocytes, is released downstream of oncogenes in breast cancer, triggering an inflammatory response by stimulating other pro-inflammatory cytokines such as IL-6, tumor necrosis factor (TNF), and IL-33 (an early warning cytokine)." (PMID 41596472, 2026). "A previous study found increased levels of TNF-a in a DMBA-induced breast cancer model." (PMID 40430573, 2025). "Neuroinflammatory and systemic inflammatory responses, particularly increases in pro-inflammatory cytokines (IL-6, IL-1β, TNF-α) and reductions in hippocampal BDNF, are consistently linked to breast cancer and chemotherapy-induced cognitive impairment in animal models." (PMID 41155372, 2025). "In a systematic review and meta-analysis, probiotic combinations of Lactobacillus, Bifidobacterium, and Streptococcus plus fructooligosaccharides reduce pro-inflammatory TNF-α levels, alleviate edema volume and improve quality of life among patients with breast cancer-related lymphedema." (PMID 41597595, 2025). "Interestingly, depletion of CTR1 largely attenuated both TNFα and LPS‐induced NF‐κB activation in breast cancer cells and mouse embryonic fibroblasts (MEFs)." (PMID 40999870, 2025). "Additionally, HBXIP upregulates TNF receptor 1 (TNFR1), forming a positive feedback loop (TNFR1/NF-κB/p38/p-STAT3/HBXIP/TNFR1) that sustains TNF-α-driven tumor progression in breast cancer." (PMID 40430573, 2025). "Ginsenoside Rh2 inhibits tumor growth via ERβ-TNFα pathway in breast cancer (MCF-7) cells." (PMID 40490812, 2025). "Interestingly, primary breast cancer cells were more enriched in genes associated with proliferation, cell cycle control, epithelial to mesenchymal transition (EMT), and tumor necrosis factor alpha (TNF-α) or interferon signaling pathways." (PMID 41303420, 2025). "Results revealed that DMBA-induced breast cancer caused a significant increase in biochemical parameters such as CEA, CA15.3, CA125, PRL, E2, urea, creatinine, ALT, AST, and ALP and a substantial increase in gene expression of TNF-α and BcL-2." (PMID 40097629, 2025). "The effects of TNF-α on VGCC of MCF-7 breast cancer cells were studied by AFM." (PMID 41415204, 2025). "This study provides unprecedented insights into TNF-α-induced calcium dysregulation in cancer cells at the single-molecule level, offering a novel approach for investigating apoptosis and advancing targeted therapies for breast cancer and other malignancies." (PMID 41415204, 2025). "IL-6 and TNF-alpha are emerging as prognostic biomarkers of poor survival in breast cancer." (PMID 40558287, 2025). "We therefore tested whether correlations between CXCL8 expression and TNF-α or TGF-β–related genes were stronger in breast cancer cell lines relative to all the cell lines tested in DepMap." (PMID 40833805, 2025). "NF‐kappa B is one of the primary transcription factors involved in the proliferation of breast cancer cells, which become activated when exposed to certain cytokines, TNF‐alpha, and interleukins, which are both necessary in the transcription process of an oncogene." (PMID 41179371, 2025). "For example, only TnT (biomarkers of damage to heart muscle) and NT-proBNP (bio-marker of heart failure) showed continuous increase post-treatment in sarcoma patients versus CRP (biomarker for inflammation) and TNFα (biomarker for heart failure) in breast cancer patients." (PMID 40014780, 2025). "Finally, analysis of transcriptomic databases of cancer cell lines revealed a significant correlation between CXCL8 and TGF-β1/TNF-α–regulated or effector genes in breast cancer." (PMID 40833805, 2025). "However, it should be emphasized that MCs have the possibility to suppress breast cancer growth through alternative mechanisms, e.g., by secretion of TNF-α and TGF-β." (PMID 41145489, 2025). "In breast cancer, TNF-α serves multiple functions in disease progression and metastasis." (PMID 41398969, 2025).
breast carcinoma (continued). "In contrast, amygdalin administrations alone or in co-administration with tamoxifen could ameliorate breast cancer by declining TNF-α, BcL-2 and attenuating the biochemical parameters." (PMID 40097629, 2025). "In this context, Ang II-treated macrophages showed an increase in TNF-α expression, which might have caused the cell necrosis observed in the MCF-7 breast cancer cell line." (PMID 40710006, 2025). "Given that TNF EVs promote MCF-7 breast cancer cell migration, we investigated whether these vesicles could also induce EMT, a process critical for tumor progression and metastasis." (PMID 40567500, 2025). "At the molecular level, chemosensitive MCF-7 breast cancer cells resistant to TNF exhibited reduced expression of TNF receptor 1 (TNFR1) and TNFR1-associated death domain protein (TRAD), which blocked extrinsic apoptosis and increased the nuclear factor-kappa B (NF-κB) survival pathway." (PMID 39863855, 2025). "In particular, we assessed the role of TGF-β1/TNF-α treatments and EMT-associated changes on this response and validated our experimental findings by conducting a comprehensive analysis of transcriptomics datasets from breast cancer cell lines." (PMID 40833805, 2025). "Additionally, the positive correlation we measured between CXCL8 and a number of TGF-β1 and TNF-α–associated genes in a large dataset of breast cancer cell lines validates our in vitro findings on a positive regulation of CXCL8 by TGF-β1 and TNF-α." (PMID 40833805, 2025). "The underlying inflammatory cause for increased sClever-1 is further supported by our data showing the induction of the release by IFNγ/TNFα, the sustained sClever-1 levels after tumor surgery and the different inflammatory cytokine profiles observed in breast cancer patients." (PMID 40756372, 2025). "It sensitizes the TNF signaling pathway to induce apoptosis and downregulate estrogen receptor expression in breast cancer, while also promoting cell proliferation and invasion in ovarian cancer, whereas its disruption in cervical and liver cancers fosters tumor progression." (PMID 40538398, 2025). "In this work, the effects of TNF-α on VGCC of breast cancer cells were studied by AFM." (PMID 41415204, 2025). "In summary, the interaction between HMGCR and TNF-α exhibits varying intensity and biological consequences depending on tumor type (e.g., breast cancer subtypes, glioblastoma) and differences in the immune microenvironment (macrophage polarization, T cell infiltration levels)." (PMID 41450917, 2025). "In addition, although hypoxia reduces TET enzymatic activity in cancer cells, hypoxia-induced increase of the 5-hmC level locally in the genomic region containing TNF-α gene of breast cancer cells is mediated by TET1 and TET3." (PMID 40764968, 2025). "Therefore, this study aims to address the following question: What is the prognostic relevance of serum IL-6 and TNF-alpha levels on overall survival and treatment response in women with breast cancer?" (PMID 40558287, 2025). "In breast cancer survivors, a high-quality diet that is typically rich in fruits, vegetables, whole grains, and polyunsaturated fatty acids has been reported to be associated with lower levels of pro-inflammatory biomarkers (e.g., CRP and TNF-α)." (PMID 40289959, 2025). "There, breast cancer cell intravasation could be visualized and quantified, demonstrating that the application of tumor necrosis factor-α (TNF- α) increased the percentage of intravasating tumor cells." (PMID 40678259, 2025). "Clinical data suggest that TNF-α levels are negative associated with breast cancer progression risk." (PMID 40909271, 2025). "This study explores the effects of treatment with low, non-toxic doses of IFN-γ and TNF-α on the susceptibility of breast cancer (BC) cell lines (MCF-7, MDA-MB-231, and MDA-MB-468) cultured in 2D and 3D as spheroids, to NK cell-mediated antitumor function." (PMID 41102150, 2025).
breast carcinoma (continued). "AR extract at 500 mg/kg body weight demonstrated the highest anti-neoplastic efficacy in a DMBA-induced rat mammary tumour model, significantly reducing tumour progression, oxidative stress, pro-inflammatory cytokines (TNF-α and NF-κB), and expression of Ki-67, MMP-9, and VEGF markers." (PMID 41158126, 2025). "APs could activate macrophages to release nitric oxide and tumor necrosis factor alpha, directly blocking breast cancer cell growth." (PMID 38466979, 2024). "An adoptive cell targeting delivery of TNFα combined with an IAP antagonist is a novel effective approach to treat breast cancer and could be expanded to treat other solid cancers." (PMID 39105847, 2024). "NOD1 functions as a sensitizer of the TNF signaling pathway, facilitating cellular apoptosis and significantly downregulating estrogen receptor expression in breast cancer cells, thereby impeding the initiation and progression of breast cancer." (PMID 39329913, 2024). "Our findings reveal that the interaction between TGF-β and TNF-α significantly amplifies MMP-9 expression in human MDA-MB-231 breast cancer cells, underscoring a complex regulatory network that extends beyond individual cytokine actions to their cooperative impact." (PMID 39351229, 2024). "Next, we asked whether TGF-β/TNF-α combined treatment of MDA-MB-231 breast cancer cells synergized the transcription of other MMPs." (PMID 39351229, 2024). "We then tested whether M-DCsTNF produce TNFα and kill breast cancer cells in combination with an IAP antagonist." (PMID 39105847, 2024). "In breast cancer cells, PD-L1 redirects TNF-induced death from apoptosis to pyroptosis." (PMID 39300122, 2024). "Additionally, invasion is directly proportional to IL-8 expression in several breast cancer cell lines and its expression in breast cancer appears to be induced by other cytokines (IL-1β, TNFα and IL-6), an/or hormones (progesterone and estrogen)." (PMID 37979099, 2024). "Treatment of breast cancer cells with TNF-α alone stimulated the release of IL-1B and IL-10." (PMID 39334821, 2024). "Both BaP and PCB exposures can result in perturbation of inflammation mediators, leading to an inflammation microenvironment (via TNF-α and NFκB leading to IL-6 upregulation) that facilitates and contributes to the migration and invasion of breast cancer cells." (PMID 39548533, 2024). "Recent studies suggest that ETV7 controls breast cancer inflammation by controlling the TNF-α axis and cross-talking with STAT3—an inflammation regulator—suggesting that VD3-GNPs therapeutically alter these pathway markers via ETV7, which is a challenge for future studies." (PMID 38791386, 2024). "Therefore, PARP1 > 6, p50 > 2, and TNF-α > 4 had a good predictive effect on postoperative metastasis of breast cancer." (PMID 38388665, 2024). "Furthermore, a comparative analysis of TNF‐α expression in the serum of breast cancer patients and healthy individuals revealed significantly greater TNF‐α expression in breast cancer patients." (PMID 39586790, 2024). "In breast cancer survivors, an aerobic and resistance training program has been associated with a significant serum levels reduction of c-reactive protein (CRP), interleukin (IL)-6, -8, and -10, and tumor necrosis factor (TNF)-α." (PMID 39458125, 2024). "Moreover, anti-PD-1 treatments can induce the production of TNFα, impairing therapeutic responses in melanoma, lung, and breast cancer in murine models." (PMID 38610706, 2024). "Similarly, Zhao and colleagues also observed higher serum levels of TNF-α, IL-1β, and Interleukin 4 (IL-4) in breast cancer patients after chemotherapy." (PMID 38348396, 2024). "Hence, upregulation of the inflammatory markers i.e., TNF-α, MMPs, HSPs and ILs have significant interplay in the onset and progression of breast cancer." (PMID 38956273, 2024).